TNF (tumor necrosis factor)
Diseases named in the same sentence as TNF in open-access papers (continued):
Sharing a sentence is not in itself a finding about the gene and the disease.
infection (continued). "Together, these results further position TNF as a critical mediator in initiating the early and late phases of neutrophil recruitment and substantiate the crucial role of neutrophils in controlling Mabs infections." (PMID 27806130, 2016). "Surprisingly, the production of TNFα, IL-17, and IL-22 were moderately elevated from the splenocytes of knockout mice, particularly at day 3 postinfection, while mostly leveling up during the late course of infection." (PMID 27046240, 2016). "However, the production of IL-6, TNFα and IL-10 in response to infection with F. tularensis LVS, S. aureus or P. aeruginosa was similar between WT (C57BL/6N) and Nlrp12−/− BMDM." (PMID 27779193, 2016). "However, low but significant amounts of TNF-α were detected in the sera of mice infected intradermally at 8 days post-infection." (PMID 28018318, 2016). "In addition, RELMβ augments interferon (IFN) γ-induced tumor necrosis factor (TNF) α secretion in thioglycollate-isolated macrophages and infection-induced intestinal inflammation." (PMID 26818807, 2016). "Following restimulation at 7 days post-infection, a similar percentage of aPKC-deficient CD8+ T lymphocytes produced IFNγ and TNFα compared to wild-type control cells; however, the percentage of aPKC-deficient cells that were capable of producing IL-2 was reduced." (PMID 26765121, 2016). "This hypothesis is supported by an in vitro study showing that early post-infection, TNFα functions primarily as a pro-survival signal and activates NF-κB." (PMID 27007501, 2016). "An infection model of Japanese encephalitis virus, a typical neurotropic virus, showed that microglial cells serve as a viral replication platform and lead to indirect neuronal killing via the secretion of TNF-α, resulting in neuronal cell death." (PMID 27279150, 2016). "Since zebrafish is a cyprinid susceptible to SVCV infection, and TNFα can exacerbate SVCV infection, we chose this amenable infection model to investigate how a virus might utilize host produced TNFα to their benefit." (PMID 27351838, 2016). "During the first 4–6 weeks after infection, the Th–1 response is stimulated by the migration of immature adult worms as characterized by increased levels of pro–inflammatory cytokines, including TNF–α, IL–1, IL–6 and IFN–γ." (PMID 27514777, 2016). "Such drugs as TNF-α inhibitor and bisphosphonates may lead to infection, pathologic femoral fractures, the impairment of fracture healing, mandibular lesions and other adverse events." (PMID 27638499, 2016). "First, during a complex polymicrobial infection, MyD88-independent signals, such as tumor necrosis factor α, may be sufficient to stimulate neurovascular inflammation and BBB breakdown." (PMID 26790027, 2016). "Therefore the increase of transcription of CXCL2, IL8 and TNF observed in the case of Th4M infection appeared to be dependent of RelAp43 and of the 4 positions mutated in Th4M." (PMID 28000711, 2016). "The higher levels of TNF-alpha that was observed 2 h after the infection with the wild type MC58 strain may be due to different physiological state of bacteria on the cultured plates." (PMID 27655040, 2016). "It has been shown that RSV increased TNF-α expression by macrophages after in vitro infection." (PMID 25658239, 2015). "In addition, infection of monocyte-derived human macrophages by influenza A viruses induced a significant up-regulation of pro- and anti-inflammatory cytokines, including TNF-α, IFN-α and IFN-β." (PMID 26274828, 2015). "Inflammation and TNFα may impact many of these processes, as part of the physiological events culminating in infection or inflammation resolution." (PMID 26323317, 2015). "HCV could induce the expression of TNF-α as early as one hour post-infection, when the semi-quantitative RT-PCR was used for the analysis." (PMID 26023919, 2015).
infection (continued). "However, expression of TNF-alpha by CD8+ T lymphocytes was increased following infection with both strains." (PMID 26147698, 2015). "Although IFN-γ was similar in both species after infection, TNF-α was much higher in BALB/c mice." (PMID 25791815, 2015). "However, pentoxifylline diminished secretion of TNF-α, IFN-γ and IL-13, cytokines associated with the outcome of infection by species of the Viannia subgenus." (PMID 26024228, 2015). "This is an important finding, as it suggests that strains of parasite that are able to induce a more balanced response, with TNF-alpha and IL-10 production, may lead to a better infection outcome." (PMID 26147698, 2015). "TNF-α is a key mediator in many experimental liver injury models, which could mediate acute and chronic inflammation and infection." (PMID 25608939, 2015). "To evaluate whether the KCs immune response following the exposure to IFN-γ and/or TNF-α is attenuated by hrHPV, we utilized a system that resembles the natural infection with hrHPV as closely as possible." (PMID 26055519, 2015). "The induction of TNF-α in Huh7 cells could be detected by immunoblot at 24 hours post-infection when the MOI used was 1 or higher." (PMID 26023919, 2015). "By comparing the effects of the parasite product hemozoin with the inflammatory mediator TNF-α on primary erythroblasts, we were able to distinguish between some of the effects of the host’s immune response to infection and that of hemozoin on the erythroid transcriptome." (PMID 25781011, 2015). "In this regard, immunogenic DCs secrete TNF-α, IL-6 and IL-1β, pro-inflammatory cytokines, which have a wide spectrum of biological activities that help to coordinate the immune response, for instance in the context of infection." (PMID 26107738, 2015). "Infection resulted in significant cell losses and up-regulation of TNF-α pro-inflammatory cytokine." (PMID 26274828, 2015). "TNF-α and IL-6 are potent proinflammatory cytokines induced during inflammation progress, accompanied with interleukin-12 (IL-12) playing the essential role in immune defense against infection." (PMID 26538826, 2015). "Similarly, the DV2-infected PBMC significantly up-regulated the amount of TNF-α secreted into the extracellular mileu from day 2 to day 4 post-infection, compared to that of the mock-infected PBMC." (PMID 26226614, 2015). "This could favor its increased phagocytosis by alveolar macrophages, and consequently the increased TNF-α production, since the binding of the receptor dectin-1 to fibrillar β-1,3 glucan is a major host fungal interaction during in vitro and in vivo infection." (PMID 26295576, 2015). "However, it is clear that the increased level of TNFα is a consequence of infection by both DENV-2 and DENV-4 viruses." (PMID 25938762, 2015). "In addition, macroscopic and histological examination showed that the lungs of TNF-a mice exhibited massive inflammatory responses after one month of infection with reduced free alveolar space and enhanced bacterial load as assessed by Ziehl-Neelsen staining." (PMID 25950182, 2015). "Furthermore, as compared with JEV-WT infection, even with serum-containing medium, JEV-NS5-M19A infection triggered significantly lower levels of IL-6 and TNF-α while producing slightly less viral RNA." (PMID 25816318, 2015). "Taken together, these data suggest that apart from the absolute amount of each cytokine, the balance between pro-inflammatory (IFN-γ and TNF-α) and anti-inflammatory (IL-10) cytokine responses to Rv2031 could determine the outcome of infection." (PMID 25897840, 2015). "This could be due to the secretion of neurotoxic molecules following infection, such as IL-1β and TNF-α." (PMID 25611061, 2015). "For TNFα, the highest induction was after infection with TA and PT isolates." (PMID 26263557, 2015). "TNFα is rapidly induced in the CNS in response to tissue injury and infection." (PMID 26345473, 2015).
infection (continued). "Previous studies have shown that curcumin inhibits NFκB pathways and production of IL-6, IL-8 and TNF-α following N. gonorrhoeae stimulation of the HeLa cervical epithelial cell line, and completely abolishes the adherence of bacteria to cells in late infection." (PMID 25856395, 2015). "In addition to infection and PAMPs (e.g., lipopolysaccharide), several cytokines (e.g., IL-8 and tumor necrosis factor) and DAMPs (e.g., uric acid) can induce NET formation in neutrophils and immune cells." (PMID 25904867, 2015). "Finally, we demonstrate that iFt-immunized FcγRIIB KO mice produce higher levels of TNF-α compared to iFt-immunized WT mice, another cytokine that also plays an essential role in survival against a primary Ft-infection." (PMID 25961064, 2015). "The extracellular Hsp70 family promotes inflammatory cytokine production and may elicit production of inducible nitric oxide synthase, interleukin (IL) 1-β, IL 6 and tumor necrocis factor α (TNFα), to guard against infection." (PMID 26288319, 2015). "Combining treatments of TNFα and IFNγ, in analogy with the in vivo cytokine expression during day 14 and 19 post infection, further decreased the intensity of the complex-I and IV staining, but this loss was alleviated by simultaneous treatment with IL-4 (P < 0.01 vs P < 0.001)." (PMID 26481427, 2015). "Similarly, TNF-α is essential for control of infection with M. tb in animals and inhibits growth of M. tb in human monocytes and alveolar macrophages." (PMID 25659138, 2015). "The FeD mice also had increased concentrations of TNFα and IL-10 after infection." (PMID 25768944, 2015). "Production of TNF has been reported to vary following infection with pathogenic or nonpathogenic mycobacterial species." (PMID 26439498, 2015). "Similarly to the previous findings, we observed that infection of hNPCs by H5N1 virus resulted in marked up-regulation of TNF-α mRNA expression." (PMID 26274828, 2015). "Exemplary contour plots displaying all possible IFN-γ/TNF-α/CD107a/proliferation-marker combinations of gated CD8β+ T cells are shown for one control animal (#3) and one infected animal (#8) at six weeks after primary infection." (PMID 25971313, 2015). "In the absence of TNF-α only R7020 at an infection of 10 MOI caused a significant increase in the adhesion of PBMCs compared to control at 24 and 72 h p.i.." (PMID 26132411, 2015). "In addition to the neutrophil response, we also observed strong induction of TNF-α in coinfected lungs as compared to the single infections." (PMID 26265006, 2015). "In the presence of antibody, infection provoked two sequential waves of TNFα transcription." (PMID 26506431, 2015). "In addition, the aerosol boosting using γ-irradiated BCG three times successively induced antigen-specific CD4+ T cells that were IFN-γ+TNF-α+IL-2+, which were maintained until at least 10 weeks post-infection." (PMID 26509812, 2015). "To do this, we performed high throughput RNA-sequencing (RNA-seq) on BMDM obtained from the same 26 age- and sex-matched AXB/BXA mice described above and their progenitors (28 samples in total), before (resting, controls) and after infection with Toxoplasma or stimulation with IFNG+TNF, or CpG." (PMID 26510153, 2015). "Surprisingly, in addition to significantly attenuated serum TNF-α and IL-6 levels, mMrp8-tolerised mice showed significantly reduced bacterial counts in the circulation and visceral organs in response to polymicrobial infection." (PMID 26329314, 2015). "Interestingly, peak levels of TNF-α transcripts occurred as early as 2h post-infection, after which they rapidly decreased by 6h and remained substantially stable up to 12h." (PMID 26241037, 2015). "Thus, as the concentration of IFNγ and TNFα increase during the latter time points of infection and clearance in WT mice, the concomitant increase of IL-4 and IL-6 appears to protect the mitochondrial functions of the colonic epithelium." (PMID 26481427, 2015).
infection (continued). "Moreover, IFNγ-induced effect on astrocyte infection was totally abrogated by the anti-TNF antibody Infliximab." (PMID 25695249, 2015). "Interestingly, infection with N. gonorrhoeae significantly induced pro (IL-6 and TNF-α) and anti-inflammatory (IL-10) cytokines in M0-MФ." (PMID 26125939, 2015). "TNFα expression is also rapidly induced in response to tissue injury and infection." (PMID 26345473, 2015). "In addition, LPS-induced macrophages produce the cytokine TNF-α during infection or septicaemia, which is capable of activation of other macrophages to participate in the host defence system." (PMID 25699985, 2015). "Moreover, significant elevation of IL-6 and INF-gamma levels and a tendency to higher levels of TNF-alpha in serum was observed after infection with the S. aureus wild-type strains at the end of the experiment." (PMID 25644616, 2015). "MHV-68 infection strongly induced immunoproteasome expression: mRNA levels of all three immunoproteasome subunits were highest at day 14 post infection and declined to control levels after 148 days, even though IFNγ and TNFα transcript levels were still increased at that time point." (PMID 25989070, 2015). "In addition and as shown in S1 Fig, CD3+ T cells were the major producers of IFN-γ, TNF-α and IL-10 in the spleens throughout the infection." (PMID 25875604, 2015). "Infection of macrophages with the intracellular mycobacterium M. smegmatis leads to an immune response with increased production of TNFα, so we tested whether particle incubation would diminish this effect." (PMID 29470790, 2015). "Considering that IFNG+TNF is important in the pathogenesis of Listeria and Hepatitis infections, it is likely that these trans-bands harbor genes that modulate the outcome of infection with these and other pathogens." (PMID 26510153, 2015). "Of note, the influx of monocytic cells into the liver during the early stages of infection has been reported before and was shown to contribute to parasite control via release of pro-inflammatory molecules such as TNF on one hand and pathogenicity development (liver damage) on the other." (PMID 25742307, 2015). "Indeed, Irg1 inhibits TLR-triggered production of IL-6 and TNFα, both of which are the only two pro-inflammatory cytokines that are partially suppressed during infection." (PMID 26510639, 2015). "Damage or infection to the endothelium causes ET-1 to bind to ETB receptors on smooth muscle cells and control the macrophages and its release of inflammatory cytokines such as tumor necrosis factor-alpha, interleukin-6, and interleukin-1." (PMID 26823980, 2015). "The higher TNF response to 1M suggests that the host is unable to eliminate the infection." (PMID 26252386, 2015). "This may suggest that IL-6 and TNF-α in the sera at the later part of infection was mostly contributed by DV NS1 protein activating TLR6." (PMID 26226614, 2015). "Infection with H. pylori significantly upregulated gastric expression of pro-inflammatory cytokines including: interferon gamma (IFNγ) (p<0.0001)., tumor necrosis factor alpha (TNFα), (p<0.0001) and Interleukin 1 beta (IL1β) (p<0.05)." (PMID 26575645, 2015). "IL-1β, together with TNF-α and IL-6, are thought to be important proinflammatory mediators in initiating and maintaining the inflammatory response to pathogen and disease development during infection." (PMID 26052324, 2015). "Therapies with immunomodulators, TNF-α inhibitors, and corticosteroids may transform an infection with T. whipplei, normally at a subacute stage, into a septic, life-threatening disease." (PMID 26215452, 2015). "The role of TNF-α during infection with M. tuberculosis is complex." (PMID 24586159, 2014). "Similarly, we observed up-regulation of IL-6, IL-1β and TNF-α in OA hOBs at peak infection (24 hpi) in our study." (PMID 25407789, 2014). "In the infection with P. yoelii YM, the DC function is affected by the presence of TNF-α." (PMID 25276830, 2014).
infection (continued). "However, apoptosis of bovine monocytes, 24 h after infection with rBRSVΔSH at an m.o.i. of 1, was low at a time when high levels of TNF-α were present in the supernatant." (PMID 24700100, 2014). "High concentrations of HCV particles could stimulate macrophages to express TNF-α, providing a direct mechanism for the virus to promote infection." (PMID 24259385, 2014). "On the other hand, TNFα exhibits host protective function against Mycobacterium tuberculosis infection, since anti-TNF-α treatment enhances the susceptibility of the infection." (PMID 24695099, 2014). "In response to infection caused by Legionella, macrophages produce inflammatory cytokines, such as interleukin 6 (IL-6), interleukin 1α (IL-1α), interleukin 1β (IL-1β), interleukin 12 (IL-12), interferon γ (INF γ), and tumor necrosis factor α (TNF-α)." (PMID 24821544, 2014). "Early studies using animal models showed that infection with Mtb HN878 induced Type I interferons, and this coincided with decreased induction of proinflammatory cytokines such as TNF-α, IFN-γ and IL-2, reduced T cell activation and increased susceptibility to infection." (PMID 24831696, 2014). "The authors also mentioned that the greater amount of TNF-α and IL-6 at the site of infection could overstimulate the recruitment of macrophages." (PMID 25538905, 2014). "Whether the levels of TNF-α produced during infection of humans with M. tuberculosis are optimal for bacterial replication or for host protection is not clear, and this likely varies with the genotype of both the infecting strain and the infected individual." (PMID 24586159, 2014). "Likewise, the proportion of CD4+ cells that individually express IFN-γ, TNF-α and IL-2 remained high eight-weeks post infection." (PMID 25500571, 2014). "The levels of TNF-α, IL-12p70, and IL-2 were lower during infection." (PMID 24741587, 2014). "Mice immunized with IB010 had significantly lower post-infection tissue bacterial loads and significantly lower serum levels of the pro-inflammatory cytokines IL-1β, TNF-α and IL-6 compared to control mice in a mouse model of disseminated A. baumannii infection." (PMID 25485716, 2014). "A recent study in sympatric ethnic groups living in Mali suggested that a few TNF diplotypes showed an interesting potential influence on severity rather than susceptibility to infection." (PMID 25124540, 2014). "However, isolate 72, released four times as much TNF-α in HEp- 2 cells in 24hs of infection (Kruskal-Wallis, p <0.05)." (PMID 25299837, 2014). "Therefore, we wanted to determine the time frame in which infection productivity is amenable to permanent modification by TNFα treatment." (PMID 24502247, 2014). "TNF-α and IL-10 expression exhibited a significant increase at the peak of infection." (PMID 24991553, 2014). "The adaptive resistance to infection caused by facultative intracellular bacteria, such as C. pseudotuberculosis, is related to CD4 T cells and, more specifically, to clones that produce Th1-type cytokines, mainly IFN-γ and TNF-α." (PMID 25179342, 2014). "However, the need for these drugs to be delivered systemically led to serious side effects such as infection, interstitial pneumonia and liver failure because generalized TNF-α inhibition suppresses the normal immune system." (PMID 24642694, 2014). "See afterwards), the increased susceptibility to bacillus of Calmette and Guérin (BCG; formerly vaccin Bilié de Calmette et Guérin) infection in mice who received anti-TNF-α antibodies and the mycobacterial susceptibility of human treated with TNF-α blockers should suggests its protective role." (PMID 24564297, 2014). "1,25(OH)2D3-VDR may exhibits its anti-inflammatory properties in MRSA-stimulated infection by inhibiting nuclear translocation of NF-kB-p65 and transcripts of IL-8, IL-6, TNFα, and NR4A2 in hMSCs." (PMID 24661536, 2014).